RPIA (ribose 5-phosphate isomerase A)
Description:
Catalyzes the reversible conversion of ribose-5-phosphate to ribulose 5-phosphate and participates in the first step of the non-oxidative branch of the pentose phosphate pathway.
Synonyms: RPI; RPIAD
Tractability: PROTAC: ubiquitination databases record sites on it; its protein half-life has been measured.
Target class: Isomerase; Enzyme
Gene: Protein-coding gene on chromosome 2 (88,691,642 to 88,750,933, forward strand). Ensembl gene ENSG00000153574.
Subcellular location (Human Protein Atlas): Nucleoplasm; Plasma membrane; Vesicles
Pathways (Reactome):
Disease: RPIA deficiency: failed conversion of R5P to RU5P; RPIA deficiency: failed conversion of RU5P to R5P
Metabolism: Pentose phosphate pathway
Gene Ontology:
Molecular function: identical protein binding; protein binding; ribose-5-phosphate isomerase activity; carbohydrate binding; monosaccharide binding
Biological process: D-ribose metabolic process; pentose-phosphate shunt; pentose-phosphate shunt, non-oxidative branch
Cellular component: mitochondrion; cytoplasm; cytosol
Genetic constraint (gnomAD): Loss-of-function variants: 26 observed, 35.4 expected, observed/expected ratio (o/e) 0.73, 90% interval 0.54 to 1.02. The upper end of that interval is the gene's LOEUF score, 1.02, which puts it in group 4 of 6, group 1 being the genes least tolerant of losing a copy. Missense variants: 379 observed, 387.38 expected, observed/expected ratio (o/e) 0.98, 90% interval 0.9 to 1.07. Synonymous variants: 163 observed, 150.84 expected, observed/expected ratio (o/e) 1.08, 90% interval 0.95 to 1.23.
Homologues: Orthologues: chimpanzee RPIA (99% identical), macaque RPIA (99% identical), pig RPIA (91% identical), dog RPIA (91% identical), mouse Rpia (88% identical), rat Rpia (87% identical), guinea pig RPIA (76% identical), tropical clawed frog rpia (57% identical), zebrafish rpia (57% identical), Drosophila melanogaster Rpi (43% identical), Caenorhabditis elegans rpia-1 (34% identical).